TBX5 (T-box transcription factor 5)
Diseases named in the same sentence as TBX5 in open-access papers (continued):
Sharing a sentence is not in itself a finding about the gene and the disease.
Holt-Oram syndrome (continued). "TBX5 is a T-box family transcription factor that regulates heart and forelimb development in vertebrates and functional deficiencies in this protein result in Holt-Oram syndrome." (PMID 31784580, 2019). "One may question why there have not been somite or vasculature defects previously associated with Holt-Oram syndrome patients or in Tbx5 mutant mice." (PMID 30532148, 2018). "Mutations in TBX5 are associated with Holt-Oram syndrome in humans." (PMID 30532148, 2018). "Notably, the investigators created a cell line modelling Holt-Oram syndrome, a congenital disorder characterized by structural cardiac and limb abnormalities, by introducing a mutation into the T-box protein 5 (TBX-5) gene." (PMID 29731778, 2018). "Additionally, we documented a novel interaction of CSRP1 with TBX5, a member of the T-box family, implicated in the Holt-Oram syndrome." (PMID 29326753, 2017). "The spectrum of mutations in Tbx5 that contribute to Holt-Oram syndrome continues to grow." (PMID 24885927, 2014). "The minor allele is predicted to bind TBX5 and AhR; the former has been linked to a number of cardiac phenotypes including Holt-Oram syndrome and atrioventricular conduction and the latter regulates cardiac size, a known risk factor for QT-prolongation and cardiac sudden death." (PMID 22912591, 2012). "Mutations of TBX5 cause Holt–Oram syndrome, which includes CHD as a clinical feature." (PMID 22011241, 2012). "Tbx5 has been identified as the Holt-Oram syndrome (HOS) causative gene." (PMID 21897873, 2011). "Dominant mutations in human TBX5 cause Holt-Oram syndrome (HOS, OMIM:142900), an autosomal dominant disorder characterized by upper limb malformations, congenital heart defects and CCS abnormalities." (PMID 39257760, 2025). "Holt-Oram Syndrome is caused by the TBX5 gene and has unknown prevalence." (PMID 39480826, 2024). "Mutations in the coding region of TBX5 invariably result in Holt-Oram syndrome (HOS), an inherited disease characterized by upper limb and cardiac deformities." (PMID 28761722, 2017). "Especially, T-box factors such as Tbx1, Tbx2, Tbx3, Tbx5, Tbx18 and Tbx20 are described to be involved in virtually all steps of cardiogenesis and mutations are associated with developmental syndromes and cardiac abnormalities like DiGeorge syndrome (Tbx1) or Holt-Oram syndrome (Tbx5)." (PMID 27907103, 2016). "Mutation in the TBX5 gene causes Holt-Oram syndrome (HOS), a heart/hand syndrome clinically characterized by upper limb and cardiac malformations." (PMID 27479212, 2016). "TBX5 is critical for forelimb development and cardiogenesis and is associated with Holt-Oram syndrome (HOS)." (PMID 26622790, 2015). "Holt-Oram Syndrome (HOS) is an autosomal dominant heart-hand syndrome caused by mutations in the TBX5 gene, a transcription factor capable of regulating hundreds of cardiac-specific genes through complex transcriptional networks." (PMID 26657204, 2015). "TBX5 is a member of the T-box transcription factor family and plays an important role in heart development and the specification of limb identity, which is very well known associated with Holt Oram syndrome, a developmental disorder affecting the heart and upper limbs." (PMID 24479926, 2014). "Mutations in human TBX5 cause Holt-Oram Syndrome (HOS OMIM142900), a disorder characterised by upper limb and heart abnormalities and mutations in TBX4 cause Small Patella Syndrome (SPS OMIM 147891), a disorder characterised by knee, pelvis and toe defects." (PMID 24651482, 2014). "Although we do not know how expression of this truncated variant of Tbx5 might affect the grafted cells, we note that mutations of this region of Tbx5 in humans are associated with Holt-Oram syndrome, which is characterized by forelimb and cardiac malformations." (PMID 24086768, 2013). "Mutation or haploinsufficiency of tbx5 in humans is related to Holt-Oram syndrome (HOS), which features congenital heart defects and forelimb deformities." (PMID 22776023, 2012).
Holt-Oram syndrome (continued). "Nevertheless, mutations in tbx5 gene underlie Holt-Oram syndrome, the majority of which is assumed as sequel "premature stops" or "developmental delay", may induce inappropriate apoptotic processes during embryogenesis and lead to the dysmorphogenesis including cardiac and limb malformation." (PMID 21982178, 2011). "Tbx5 mutations in humans cause Holt-Oram syndrome (HOS), an autosomal dominant condition characterized by a familial history of congenital heart defects and preaxial radial ray upper-limb defects." (PMID 21982178, 2011). "Autosomal dominant Holt-Oram syndrome (HOS) is caused by mutations in the TBX5 gene and is characterized by congenital heart and preaxial radial ray upper limb defects." (PMID 18828908, 2008). "For example, TBX5 knockout studies have elucidated the gene’s role in Holt–Oram syndrome (HOS), while the correction of TBX5 mutations restored normal gene function and enhanced understanding of regulatory pathways." (PMID 40564627, 2025). "Recent investigations into the role of TBX5 in Holt Oram syndrome (HOS) have presented another example of the power of functional genomics with hiPSCs to identify gene interactions causing disease phenotypes in vivo." (PMID 35487213, 2022). "TBX5 heterozygous loss-of-function mutations underlie Holt-Oram syndrome (HOS), an autosomal dominant developmental disorder characterized by skeletal abnormalities and, frequently, cardiac defects including atrial septal defects (ASDs), ventricular septal defects (VSDs), and conduction defects." (PMID 35835508, 2022). "TBX5 and TBX3 are required for formation and normal development of forelimbs; mutation in these genes is associated with Holt-Oram syndrome." (PMID 36360176, 2022). "There is only one case report in the published literature linking TBX5 with the development of PCa, and the patient in the case report had Holt–Oram syndrome." (PMID 31963871, 2020). "TBX5 was identified as the gene responsible for Holt-Oram syndrome, a syndrome that is clinically characterized by radial ray deficiencies and cardiac defects, such as atrial septal defects (ASD) and ventricular septal defects (VSD)." (PMID 32236096, 2020). "Mutations in the human TBX3 and TBX5 genes cause ulnar-mammary syndrome (UMS, OMIM 181450) and Holt-Oram syndrome (HOS, OMIM 142900), respectively." (PMID 30630509, 2019). "The forelimbs seemed completely normal even at this stage, which was a significant difference between the phenotype of the Tbx5ua KD mice and that of the mouse model of Holt-Oram syndrome (i.e., Tbx5 heterozygous knockout)." (PMID 30587117, 2018). "Mice that are haploinsufficent for Tbx5 mimic the Holt-Oram syndrome phenotype, having both defective heart and forelimb tissues." (PMID 30532148, 2018). "One such example is Holt-Oram syndrome (HOS), which is characterized by congenital cardiac defects and forelimb anomalies, mainly attributed to mutations in the TBX5 gene." (PMID 29250101, 2017). "By linking the action of Tbx5 to symmetrical limb formation, the authors provide an explanation for why Holt-Oram syndrome patients have more severe defects in the left arms than right." (PMID 27992425, 2016). "In Holt-Oram Syndrome (HOS), caused by mutations in TBX5, affected individuals have left-biased upper/forelimb defects." (PMID 27992425, 2016). "A role of human TBX5 in eye development is apparent from the frequent ophtalmological symptoms of patients suffering from Holt Oram Syndrome (TBX5 haploinsufficiency)." (PMID 25781970, 2015). "Tbx5 null mice possess a deformed linear heart tube and underdeveloped atria while heterozygous Tbx5 mice model heart and limb abnormalities observed in Holt–Oram syndrome, potentially explaining cardiac conduction system defects seen in these patients." (PMID 23934094, 2014). "Another transcription factor which has been described in the context of the Holt–Oram syndrome is the T-box transcription factor Tbx5." (PMID 23760510, 2013).
Holt-Oram syndrome (continued). "In mice, the Holt-Oram syndrome recreated with the heterozygous Tbx5 model is the best example of a dosage dependent phenotype-genotype correlation." (PMID 23226213, 2012). "Tbx5 haploinsufficiency in mice accurately mimics the phenotype found in patients with Holt-Oram syndrome." (PMID 22589735, 2012). "Tbx5 function in the heart is gene dosage sensitive, as both haploinsufficiency and gene duplication give rise to Holt−Oram syndrome (HOS)." (PMID 23226307, 2012). "Here, we show that myocardin directly interacts with Tbx5, a member of the T-box family of transcription factors involved in the Holt-Oram syndrome." (PMID 21897873, 2011). "Some studies indicate that these patterns of Tbx5 expression provide an embryologic basis for the prevalence of atrial and ventricular septal defects observed in patients with Holt-Oram syndrome." (PMID 20219112, 2010). "As a master regulator of cardiac gene expression, tbx5 has been shown to be very sensitive to its own gene dosage, where too few (haploinsufficiency) or too many copies (gene duplication) lead to Holt–Oram syndrome, which is marked by congenital malformations of the heart." (PMID 38787147, 2024). "Interestingly, duplications of TBX5 as well as intragenic duplications have been reported in families with (atypical) Holt-Oram syndrome including cardiac defects." (PMID 36715501, 2023). "Mechanistic work revealed that Tbx5 and Nk2.5 synergistically interact to promote the expression of the gap junction protein Cx40 (Gja5), reduction of which is assumed to contribute to the cardiac anomalies in Holt-Oram syndrome." (PMID 37125615, 2023). "Since the mother and brother are healthy, and the patient does not have any heart-related problems, the TBX5 variant alone was excluded as being disease causing for the Holt-Oram syndrome in this family." (PMID 34149817, 2021). "Importantly, the phenotypes of Holt-Oram syndrome show a high degree of variance, indicating that the dose of TBX5 is crucial in normal heart development." (PMID 30587117, 2018). "Indeed, disruptions to the TBX5/SRSF2 equilibrium result in Holt-Oram Syndrome, which include cardiac conduction diseases such as AF that can occur alone or in combination with atrial and ventricular septal defects." (PMID 29848314, 2018). "In particular, TBX5 gene defects were shown to be responsible for the most common prototypical heart–hand syndrome type I, or Holt-Oram syndrome (HOS, MIM1 142900) characterized by cardiac septal defects, conduction system disease and radial ray anomaly of forelimb skeleton." (PMID 29963074, 2018). "TBX5 may affect the development of paroxysmal AF, based on the research of a large atypical Holt-Oram syndrome family." (PMID 23717681, 2013). "Holt-Oram syndrome and Duane-radial ray syndrome, which we discuss in Box 3, present similar phenotypes due to genetic perturbations in a shared molecular pathway: Tbx5 acts directly upstream of Sall4 during heart and appendage development in mice and in zebrafish." (PMID 37125615, 2023). "In humans, these heterozygous conditions can lead to syndromes, including Holt-Oram Syndrome (HOS, TBX5), ulna mammary syndrome (UMS, TBX3), DiGeorge syndrome (TBX1), spondylocostal dysostosis (TBX6) and cleft palate and ankyloglossia (TBX22)." (PMID 32855167, 2020). "Duane-radial ray syndrome (DRRS; MIM #607323) and Holt-Oram syndrome (HOS; MIM #142900) are both autosomal dominant conditions caused by mutations in SALL4 and TBX5 genes, respectively." (PMID 31388035, 2019). "Mutations in human, TBX5 and TBX4, areassociated with Holt-Oram syndrome (HOS), and SmallPatella syndrome (SPS),respectively, and both syndromes are characterised by various limb defects in additionto other abnormalities." (PMID 20152185, 2010). "The patient carrying a contiguous microdeletion of TBX5 and TBX3 genes displays features of Holt–Oram Syndrome (HOS) and ulnar-mammary syndrome (UMS)." (PMID 27722056, 2016).
Holt-Oram syndrome (continued). "Previously, we showed that KLF13 is a TBX5 cofactor and that KLF13 may be a genetic modifier of Holt-Oram Syndrome and possibly other congenital heart diseases." (PMID 32293321, 2020). "In this study, although the variant P163S eliminated synergistic activity with TBX5, the patient did not have typical Holt-Oram Syndrome or other TBX5-related features." (PMID 32293321, 2020). "In addition to single nucleotide mutations, there are several reported cases of contiguous microdeletions at 12q24.21 locus encompassing both TBX3 and TBX5 genes and giving rise to phenotypes that combine UMS and Holt-Oram syndrome features." (PMID 29963074, 2018). "The most common form is Holt-Oram syndrome (HOS; MIM No. 142900) caused by a loss-of-function mutation in the TBX5 gene located on chromosome 12q24.1 (heart-hand syndrome I)." (PMID 21034446, 2010).
congenital heart disease (30 papers, 2010 to 2025). A heart disease that is present at birth. "Missense mutations of TBX5 have been associated with multiple types of congenital heart diseases (CHDs), such as Holt–Oram syndrome (HOS), atrial septal defect (ASD), and ventricular septal defect (VSD)." (PMID 40751491, 2025). "Together, our findings provide biophysical and biochemical mechanisms that can be further explored to establish causality between TBX5 missense mutations and the development of congenital heart diseases." (PMID 40751491, 2025). "Mutations in TBX5, a transcription factor necessary for heart development, are among the causes of congenital heart diseases." (PMID 40751491, 2025). "TBX5 is a key regulator of heart development, and TBX5-dependent pathways are associated with heart development, CM function, and congenital heart disease." (PMID 38528561, 2024). "Research on specific SNPs in TBX5 also have been performed and revealed a significant association with congenital heart disease." (PMID 38019868, 2023). "TBX20, a cardiac TF regulated by TBX5, is essential for proper heart development with mutations that have been associated with congenital heart diseases." (PMID 37926287, 2023). "scRNA-seq of hiPSC mutants for TBX5 enabled the construction of gene regulatory networks (GRNs) linked to congenital heart disease." (PMID 35487213, 2022). "TBX5 is primarily linked to congenital heart disease; however, the homologs TBX2 and TBX3, which share DNA binding consensus with TBX5, are associated with cancer and invasive cellular behavior." (PMID 26549256, 2015). "The importance of the interaction of GATA4 and Tbx5 for heart development has been suggested by human genetics studies which have reported patients with congenital heart disease carrying the G296S mutation in the GATA4 protein." (PMID 25241353, 2014). "Human mutations in TBX5 cause congenital heart disease (CHD), although the underlying mechanism is unknown." (PMID 31953255, 2020). "In addition to two polymorphisms of NKX2‐5 (rs2277923, rs28936670) variant in the cardiac septal defect, two variants in GATA4 (rs368418329, rs56166237) and one variant in TBX5 (rs6489957) seem to have a role in the pathogenesis of congenital heart disease." (PMID 30834692, 2019). "Regulatory variation in a TBX5 gene enhancer causes isolated congenital heart disease." (PMID 31775637, 2019). "Another example of a physiologically important partnering of GATA4 was provided by the finding that the G296S mutation affects the interaction between GATA4 and Tbx5 and it leads to congenital heart disease in patients, while in homozygous mutant mice it causes mid-gestation lethality." (PMID 25241353, 2014). "Congenital heart disease (CHD) represents a prevalent group of structural cardiac anomalies often associated with alterations in key transcription factors including NKX2-5, TBX5, and, particularly, GATA4." (PMID 40430071, 2025). "Previous reports have shown that GATA4 and TBX5 have a significant impact on congenital heart disease." (PMID 39375485, 2024). "A homozygous point mutation in a highly conserved enhancer region downstream of the developmental transcription factor TBX5 has been reported in patients with congenital heart disease." (PMID 35997367, 2022). "GRNs showed that TBX5 dosage is critical for maintaining cardiac network stability and pointed out potential genetic interactions disrupted in TBX5-dependent congenital heart defects (CHDs), such as with MEF2C." (PMID 35487213, 2022). "Over the past 20 years, mutations of proteins expressed in human, mouse, and Xenopus hearts have shown a similar phenotype, such as the Holt Oram disease/ T-box transcription factor 5 (TBX5)- and Tbx20-related congenital heart disease." (PMID 31490923, 2019). "Mutations in TBX5 gene have been implicated in HOS, a variety of congenital heart diseases, dilated cardiomyopathy and atrial fibrillation." (PMID 31775637, 2019).
congenital heart disease (continued). "This study aimed to investigate the relationship between TBX5 3′UTR variants and risk for congenital heart disease (CHD) susceptibility in two Han Chinese populations, and to reveal its molecular mechanism." (PMID 28761722, 2017). "Further, TBX5 expression from human adult ischemic or dilated cardiomyopathy were substantially abundant, indicating its participation may beyond congenital heart disease." (PMID 38525280, 2024). "Although we first postulated that a functional variant in the TBX5 3′UTR may increase the risk of CHD, a recent study indirectly supported our findings by reporting that a TBX5 enhancer variant causes isolated congenital heart disease." (PMID 28761722, 2017). "We screened the TBX5, GATA4, and NKX2.5 genes for mutations, by direct sequencing, in 32 unrelated patients presenting classical or atypical HOS, isolated congenital heart defects or isolated upper-limb malformations." (PMID 21637475, 2010). "On the other hand, it seems that the role of genes, such as GATA4, TBX5, NKX2-5, HOMEZ, PLAGL1, and CITED2, in heart development is significant, as numerous studies on knockout mice report that mutations in these genes are frequently associated with VSD or other congenital heart anomalies." (PMID 39466144, 2025). "Furthermore, mutations in TBX5 and TBX20 are associated with congenital heart disease in humans." (PMID 23533583, 2013).